CD4 (CD4 molecule)
Diseases named in the same sentence as CD4 in open-access papers (continued):
Sharing a sentence is not in itself a finding about the gene and the disease.
HIV-1 infection (continued). "The impact of sustained Tat-SF1 suppression on HIV-1 replication kinetics was assessed in CD4+ T cell-derived SupT1 cells, a model that more closely simulates natural HIV-1 infection than TZM-bl cells." (PMID 23153325, 2012). "Nup62 knockdown in CD4+ T cells and macrophages significantly inhibited HIV-1 infection and by qPCR analysis, the block of the infection was pinpointed to viral integration and in a much lesser extent to the nuclear import step." (PMID 22928108, 2012). "Lastly, Dual sh1005/sh516-transduced HSPC-derived CD4+ T-cells resisted depletion by both R5- and X4- tropic HIV-1 infection in 5/5 and 3/4 transplanted hu-BLT mice, respectively." (PMID 23300932, 2012). "We first sought to identify single HLA alleles that are predictive of better or worse disease outcome with respect to viral load and CD4+ T cell count in our cohort of 2031 Southern African adult subjects with C-clade HIV-1 infection." (PMID 23094091, 2012). "By doing so, we define the virus-induced genes and microenvironment most favorable to allow productive HIV-1 infection and show that even within a population of activated CD4+ T cells, the permissive environment for HIV-1 infection is very specific." (PMID 22876188, 2012). "Because the primary targets of HIV-1 infection are CD4+ cells that play key roles in antiviral immunity, the dysregulation of autophagy in these cells further promotes the chronicity of HIV-1 infection." (PMID 22606989, 2012). "Several gene therapy strategies are being studied in order to construct CD4 cells resistant to HIV-1 infection by a population of anti-HIV-1 antisense RNA producing lymphocytes." (PMID 22848825, 2012). "In yet another study, it was shown that another member of the Trx superfamily, glutaredoxin-1 (Grx1), can reduce disulfide bonds in both CD4 and gp120, and its inhibition results in reduced HIV-1 infection." (PMID 23206338, 2012). "Much of the damage related to HIV-1 infection, including rapid depletion of CD4 cell numbers in the gut, occurs early in infection whereas clinical manifestation are only detected years later." (PMID 22412885, 2012). "In vivo infection of macaques with SHIVmn229 and SIVmac251 resulted in CD4+ iNKT depletion similar to human HIV-1 infection, and iNKT depletion was tightly correlated to CD4 decline." (PMID 22916008, 2012). "CD34+ haematopoetic cells (HPCs) also serve as a viral reservoir, since a subpopulation of CD34+ HPCs expresses CD4 and CCR5 and/or CXCR4 and these cells are susceptible to HIV-1 infection." (PMID 22548060, 2012). "Among African serodiscordant couples, there is a high rate of mortality attributable to HIV-1 infection at CD4 counts above the current threshold (200 – 350 cells/μl) for ART initiation in many African countries." (PMID 23130818, 2012). "Several studies have reported that SPs inhibited HIV-1 infection by disrupting the interaction between gp120 and CD4, by either binding to CD4 or to gp120." (PMID 22558266, 2012). "DC-SIGN molecules on the cell surface enhance HIV-1 infection by capturing virions and transmitting them to CD4+ T-lymphocytes." (PMID 22808239, 2012). "It has been known for many years that infection of activated CD4+ cells results in productive HIV-1 infection, whereas infection of un-activated CD4+ cells is less efficient and typically results in abortive infection." (PMID 22720026, 2012). "HIV-1 is known to replicate poorly in myeloid cells; however, these cells play an important role in promoting dissemination of HIV-1 to CD4+ T-lymphocytes, the major target of HIV-1 infection." (PMID 23231760, 2012). "In contrast to resting CD4+ T cells in the periphery, these cells can undergo productive HIV-1 infection." (PMID 23170164, 2012). "Conceivably, elite controllers of HIV-1 infection, who exhibit undetectable viral loads and maintain stable CD4+ T cell counts, differ in their regulation of autophagy." (PMID 22606989, 2012).
HIV-1 infection (continued). "Our time-course analysis of DCs infected with replication-competent WT HIV-1 and Nef-mutated viruses suggest that HIV-1 infection of DCs can down-regulate DC-SIGN and CD4 expression in a largely Nef-independent manner." (PMID 22479639, 2012). "HIV-1 infection begins with the binding of trimeric viral envelope glycoproteins (Env) to CD4 and a co-receptor on target T-cells." (PMID 22807678, 2012). "This inactive form of APOBEC3G can be found in tissue resident naïve or memory CD4+ T cells, which are permissive to HIV-1 infection." (PMID 22548060, 2012). "HIV-1-specific CD4+ T cells and the pool of central memory CD4+ T cells are also preserved despite immune activation due to HIV-1 infection." (PMID 23243424, 2012). "Blocks to HIV-1 infection in resting CD4+ T-lymphocytes include the entry step, completion of reverse transcription (RT) of incoming viral RNA genomes into DNA, nuclear import and integration of the viral genome, as well as transcription of viral genes." (PMID 23227982, 2012). "We characterized the profile of CD4+ T cells most permissive to productive HIV-1 infection by staining for CD45RO, CD27 and HSA." (PMID 22876188, 2012). "In spite of extensive research over the past three decades, the mechanism of CD4+ T-cell depletion during the course of HIV-1 infection is still debated." (PMID 22511868, 2012). "Our results indicate that Vpr significantly enhances single-cycle HIV-1 infection in PBMCs, CD4+ T-cells and MDDCs." (PMID 22570689, 2012). "Acting as a deoxynucleoside triphosphate (dNTP) triphosphohydrolase, SAMHD1 hydrolyzes dNTPs and restricts HIV-1 infection in macrophages and resting CD4+ T-cells by decreasing the intracellular dNTP pool." (PMID 23231760, 2012). "In vitro HIV-1 infection of either CD4 expressing T- cell lines or stimulated peripheral blood mononuclear cells (PBMC's) upregulates the production of HERV-K RNA and proteins compared to non-infected cells." (PMID 22248111, 2012). "We calculated the excess medical mortality attributable to HIV-1 infection by categories of CD4 count and plasma HIV-1 RNA, after adjusting for ART use." (PMID 23130818, 2012). "This is in great contrast to the extensive dependency on signaling molecules observed during cell-cell fusion or HIV-1 infection of resting CD4 T cells, which appears to require a different signaling environment." (PMID 22640593, 2012). "Several months after HIV-1 infection, blood CD4+ T cell counts, plasma RNA viral load (VL) and CD8+ T cell activation levels reach the so-called set-point." (PMID 23056251, 2012). "Our results suggest that HIV-1 infection induces a pattern of T cell activation/exhaustion, affecting both CD4+ and CD8+ T cells, despite increased polarization towards a regulatory profile." (PMID 22276176, 2012). "A retrospective observational cohort of 66 adult patients with HIV-1 infection who interrupted HAART with a CD4+cell count ≥350 cells/μL and undetectable viral load (VL) was performed." (PMID 23095460, 2012). "To better understand the role of Nef in HIV-1 infection of resting CD4+ T cells, we investigated the effect of WT HIV-1 and Nef-mutated viruses on the activation of resting CD4+ T cells and viral replication using cells from three different donors." (PMID 22479639, 2012). "We also saw a gradual decline of the CD4+T cell count, widespread immune activation, up-regulation of inflammation marker and microbial translocation after HIV-1 infection." (PMID 22675567, 2012). "Studies on HIV-1+ non-progressors to date have used varying definitions based on duration of HIV-1 infection and CD4+ T-cell counts to identify atypical patient groups." (PMID 22363409, 2012). "In vitro, breast milk mucin (MUC1) effectively blocks binding and transfer of virus from dendritic cells (DC) to CD4+ T cells and inhibits HIV-1 infection." (PMID 22952771, 2012).
HIV-1 infection (continued). "Compared with activated CD4+ T-cells that support productive HIV-1 infection, resting CD4+ T-cells have lower levels of dNTPs, which limit efficient HIV-1 reverse transcription and thereby block HIV-1 infection." (PMID 23092163, 2012). "Although it is now agreed that iNKT cells, particularly CD4+ iNKTs, are depleted during HIV-1 infection, less data is available to clarify the impact of this depletion on disease progression and viral pathogenesis." (PMID 22916008, 2012). "To investigate the effect of an HIV-1 infection on the population of human CD4+ T cells in HIV-1-infected hNOK/B51Tg and hNOK mice, we analyzed the phenotype of these cells among PBMCs from the mice every 2 weeks post-infection." (PMID 22880104, 2012). "CD4+ lymphocytes are the main targets for HIV-1 infection with various sub-populations infected to a different extent." (PMID 23185351, 2012). "Previous studies have indicated that wild-type Nef plays an important role in HIV-1 infection and activation of CD4+ T cells." (PMID 22479639, 2012). "Compared with activated CD4+ T-cells that support HIV-1 infection, resting CD4+ T-cells have lower levels of dNTPs, which limit HIV-1 reverse transcription." (PMID 23092163, 2012). "Would an increase in miRNA-122 expression upon HIV-1 infection of CD4+ T cells, monocytes and macrophages explain the ability of HCV to infect cells beyond hepatocytes in co-infected patients?" (PMID 23202492, 2012). "Among them macrophages were described, more than twenty five years ago, to carry markers of productive HIV-1 infection in vivo, although they express only low levels of CD4." (PMID 23035819, 2012). "Massive CD4 T cell depletion in HIV-1 infection can be accounted for by a direct effect of the virus on gut lymphoid tissue during initial stages of infection and this is associated with aberrant immune activation." (PMID 22970212, 2012). "CCR5 expression on CD4+ CM subset was higher in the CD4 Low group compared with the CD4 High group during the 1st year of HIV-1 infection." (PMID 23185351, 2012). "SAMHD1 silencing also enhances HIV-1 infection of resting CD4+ T cells, suggesting that SAMHD1 also restricts HIV-1 infection in quiescent T cells." (PMID 23344558, 2012). "Mechanistically, PA inhibits HIV-1 infection by binding to a novel pocket on the CD4 receptor and blocks efficient gp120-to-CD4 attachment." (PMID 21949756, 2011). "In HIV-1 infection, Vpu antagonizes tetherin-mediated restriction by downmodulating tetherin from the cell surface; compared to CD4+ T-cells, MDMs express higher endogenous tetherin levels than CD4+ T-cells." (PMID 22110710, 2011). "Previous studies have demonstrated the ability of blood and tissue DC to transfer HIV-1 infection to CD4+ T cells." (PMID 21639903, 2011). "HIV-1 infection was significantly enhanced in primary CD4+ T cells activated by fungus-pulsed MDDCs compared with control MDDCs without fungi." (PMID 22110688, 2011). "CD4+CD25hiFoxP3+ immunosuppressive regulatory T (Treg) cells have been implicated as a possible cause of immune dysfunction during FIV and HIV-1 infection, as they are capable of modulating virus-specific and inflammatory immune responses." (PMID 21364928, 2011). "In this study, the CD4-independent HIV-1 infection was attenuated by BFLA-1, chloroquine, dynasore, and Esp15-DN." (PMID 21541353, 2011). "This suggests that combined treatment of mature CD4+ T cells with X4-ZFNs and R5-ZFNs can provide permanent protection against HIV-1 infection." (PMID 21533216, 2011). "HIV-1 Nef protein accelerates CD4 internalization and degradation inthe lysosomes, and at the late stages of HIV-1 infection, CD4 can betargeted for proteasomal degradation by HIV-1 Vpu." (PMID 21533244, 2011). "Our results suggest that the effects of HIV-1 infection and aging on the the naïve CD4+ T-cell compartment are both additive and distinct, and that HIV-1 induced impairments are not fully restored to an age-appropriate status by ART." (PMID 21298072, 2011).
HIV-1 infection (continued). "While these data accord with the majority of studies examining telomere length in total, or effector/memory, CD4+ T-cell populations during HIV-1 infection, they do conflict with the findings of Miedema and colleagues." (PMID 21298072, 2011). "The down-regulation of CD4, one of the hallmarks of HIV-1 infection, leads to the efficient assembly of viral particles, to the disruption of CD4-based immune responses and contributes to avoid superinfection." (PMID 22103833, 2011). "HIV-1 infection is characterized by chronic immune activation which, in combination with the progressive depletion of CD4+ T cells, profoundly perturbs antigen-specific T cell responses." (PMID 21750674, 2011). "This strongly indicates that the CD4-independent HIV-1 infection occurs through acidic endosomes, as in the case of other retroviruses." (PMID 21541353, 2011). "X4 HIV-1 infection of immature (CD3-CD4+/loCD8-) thymocytes located in the thymic cortex has been shown to prevent their maturation into mature functional CD4+ T cells in vitro." (PMID 21639903, 2011). "It is well established that HIV-1 infection typically involves an interaction between the viral envelope protein gp120/41 and the CD4 molecule followed by a second interaction with a chemokine receptor, usually CCR5 or CXCR4." (PMID 21284901, 2011). "HSV-2 infection of DCs significantly increased HIV-1 infection in CD4+ T cells in the DC-T cell co-cultures." (PMID 21738472, 2011). "Upregulation of surface tetherin in macrophages by HIV-1 infection appears to be induced by Nef, and HIV-1 replication in a human CD4+ cell line causes tetherin induction after an initial down-modulation of tetherin." (PMID 21504576, 2011). "As in studies in developed countries, HIV-1 infection and immune function, as measured by nadir CD4+ count, were the most powerful predictors of incident and persistent GWs, even after adjusting for the presence of HPV." (PMID 21251265, 2011). "The protective role of CD4+ T cell responses in HIV-1 infection has been suggested in previous studies." (PMID 21752277, 2011). "In conclusion, we document a marked difference in CD4+ T-cell decline and time to treatment comparing CRF01_AE and non-CRF01_AE HIV-1 infection in Singapore." (PMID 21298051, 2011). "The mean number of CD4+/CCR5+ cells in participants at a late time point in HIV-1 infection was 2.2 fold lower compared to those at early stage groups, 12 and 26 respectively (p = 0.0113, unpaired t-test; Figure." (PMID 21655330, 2011). "We demonstrated that IFNα treatment of DCs restricted DC-mediated HIV-1 infection and transmission to CD4+ T cells." (PMID 21504576, 2011). "The dynasore treatment did not affect the cell surface expression of CXCR4, demonstrating that dynasore treatment attenuated the CD4-independent HIV-1 infection through a mechanism other than the suppression of CXCR4 expression." (PMID 21541353, 2011). "The first step of HIV-1 infection involves interaction between the viral glycoprotein gp120 and the human cellular receptor CD4." (PMID 22312332, 2011). "Lastly, bDLE was capable of rendering CD4 expressing cells resistant against HIV-1 infection by residual active virus for several hours." (PMID 22044844, 2011). "The absolute number of B cells correlated directly with the CD4+ T cell count, a primary marker of disease progression in HIV-1 infection (Spearman, p = 0.002, rho = 0.43)." (PMID 21886768, 2011). "We wanted to investigate the role of Tnp3 in cell types relevant to HIV-1 infection, including macrophages and CD4+ T-cells." (PMID 21901095, 2011). "Seborrheic dermatitis has been linked to depression of T cell function, and in patients with HIV-1 infection, it appears at early stages and worsens as the CD4+ lymphocyte count declines." (PMID 21261982, 2011).
HIV-1 infection (continued). "We screened 149 abstracts addressing the topic of the rate of fall in CD4 counts in untreated HIV-1 infection, and we identified 40 publications that described mathematically the natural evolution of CD4 counts in untreated HIV-1 infected patients." (PMID 21494630, 2011). "To understand more clearly the role of CD4 in HIV-1 infection, we investigated the contribution of envelope glycoprotein changes to the CD4 independence and neutralization sensitivity of an HIV-1 variant selected to replicate in CD4−CCR5+ cells." (PMID 21731494, 2011). "Our observation of telomere shortening in even the least differentiated naïve CD4+ T-cells (i.e.,the CD31+CD4+ T-cell subset) in response to both aging and HIV-1 infection is intriguing and implies possible telomere shortening in an earlier progenitor cell." (PMID 21298072, 2011). "In the early event of HIV-1 infection, the viral glycoprotein gp120 attaches the virus to the cell by binding to its receptor CD4 on cells of the host's immune system." (PMID 21435237, 2011). "HIV-1 negative (n = 40) and HIV-1 positive (n = 103) individuals from a cohort in Rakai, Uganda, were chosen to study CD4 T cell activation in untreated HIV-1 infection." (PMID 21526194, 2011). "Due to itsimportance in the context of HIV-1 infection, revealing the CD4“interactome” can lead to the discovery of important proteins in thepathogenesis of the virus." (PMID 21533244, 2011). "Our findings suggested that bDLE highly inhibited HIV-1 infection at all stages, possibly due to viral Tat protein down-regulation (Tat activates β-galactosidase indicator gene expression in HeLa-CD4-LTR-β-gal cells)." (PMID 22044844, 2011). "HIV-1 infection results in cell cycle arrest at the G2 phase accompanied by massive CD4+ T-cell death." (PMID 21569376, 2011). "The mechanism by which the uninfected CD4+ T cell population is inexorably depleted during the asymptomatic phase of HIV-1 infection remains elusive." (PMID 21943198, 2011). "The functional relevance of Env-specific CD4+ T-cell responses or GPN-specific CD8+ T-cell responses in setting of vaccination for prevention of HIV-1 infection needs to be further explored." (PMID 21909386, 2011). "Lesions or microtrauma would also render the outer foreskin and/or shaft of the penis vulnerable to HIV-1 infection, providing access to an abundance of cells expressing CD4, as well as CCR5 and CXCR4." (PMID 21284905, 2011). "So, Vpr can contribute to the depletion of CD4+ T lymphocytes either directly or by enhancing Fas-mediated apoptosis during acute HIV-1 infection." (PMID 21994747, 2011). "Comparative studies between CD4-dependent and –independent HIV-1 infections will pave the way to clarification of the novel mechanisms that have not been disclosed using only CD4-dependent HIV-1, as we have already reported." (PMID 21541353, 2011). "Limited production of CD4+ T cells and delayed recovery of thymus function following treatment of HIV-1 infection are significant problems even with the availability of highly active antiretroviral therapy." (PMID 21639903, 2011). "HIV-1 infection results in extensive viral replication and progressive CD4+ T cell depletion in the vast majority of patients." (PMID 22141397, 2011). "We showed that the HTLV-1 Tax protein is a major contributor to the difference between HTLV-1 and HIV-1 infection in Jurkat-Raji/CD4 cocultures and that Tax significantly enhanced HTLV-1 cell-to-cell infection." (PMID 20195464, 2010). "HIV-1 infection results in a gradual decline in the number of CD4+ T cells, leading to the development of AIDS." (PMID 21129188, 2010). "Again an up-regulation of DCIR expression was detected in such samples, which supports the concept that HIV-1 infection promotes expression of this C-type lectin receptor on the surface of circulating CD4+ T cells." (PMID 21085612, 2010).